SRSF7 (serine and arginine rich splicing factor 7)
Diseases named in the same sentence as SRSF7 in open-access papers:
SRSF7 is named in the same sentence as 34 diseases in open-access papers, as found by Europe PMC text mining. Sharing a sentence is not in itself a finding about the gene and the disease. The quoted sentences say what the papers report.
lung carcinoma (4 papers, 2021 to 2024). "Overexpression of SRSF5 and SRSF7 in lung cancer and colorectal cancer tissues, and knockdown of SRSF7 induced apoptosis in colorectal and lung cancer cells." (PMID 39286028, 2024). "SRSF7 is upregulated in colon and lung cancer, and its knockdown inhibited cell proliferation and increased apoptosis." (PMID 35612714, 2022). "For example, inhibition of SRSF7 promotes apoptosis in colon and lung cancers." (PMID 33842552, 2021). "Reduced cytoplasmic availability of the Strubbelig-receptor family protein group (SRSF1, SRSF7, SRSF9) can determine autophagy suppression regulated by SRSF1 and apoptosis of colon and lung cancer cells induced by SRSF7 and SRSF9 reduction." (PMID 36066672, 2022). "Reduced availability of the SRSF1 protein, which regulates autophagy activation, as well as SRSF7 and SRSF9, which induce apoptosis in colon and lung cancer cells by controlling apoptosis." (PMID 36066672, 2022).
renal carcinoma (4 papers, 2021 to 2022). A carcinoma arising from the epithelium of the renal parenchyma or the renal pelvis. "MicroRNAs modulate the expression of osteopontin splice variants in renal cancer cells by targeting SRSF7 splicing factor." (PMID 33842552, 2021). "In lung and renal cancer cell lines, SRSF7 was shown overexpressed and SRSF7 knockdown inhibited proliferation and enhanced apoptosis." (PMID 35463320, 2022). "Silencing of SRSF7 was shown greatly reduce cell proliferation in renal cancer cells." (PMID 35463320, 2022). "Additionally, miR-181a-5p directly decreases both SRSF7 mRNA and protein levels, downregulating SRSF7-mediated AS, which reduces renal cancer cell proliferation." (PMID 33407694, 2021). "SRSF7 was also shown to regulate and is regulated by miR‐30a in renal cancer, but there is no information regarding the functional relationship between miR‐30e and SRSF7 in PCa available." (PMID 35612714, 2022).
breast carcinoma (3 papers, 2020 to 2024). "Among all the RBPs (HNRNPU, HNRNPK, RBM5, HNRNPLL, HNRNPH1, HNRNPM, HNRNPA2B1) screened, only SRSF7 (also known as 9G8) was substantially upregulated in hypoxia-treated breast cancer cells." (PMID 34362878, 2021). "Finally, we found that HNRNPL and SRSF7 were both significantly overexpressed in basal tumors when compared to other breast cancer subtypes and to normal tissue samples." (PMID 38664594, 2024). "Furthermore, E2F1 skews the cancer spliceome by upregulating splicing factor SRSF7 in hypoxic breast cancer cells." (PMID 34362878, 2021). "Furthermore, the functional relevance of E2F1 upregulation in oxygen-deprived breast cancer cells is explicated by the finding that E2F1 alters the cancer spliceome by upregulating splicing factor SRSF7 under hypoxia." (PMID 34362878, 2021).
colon cancer (2 papers, 2022). "SRSF7 was found overexpressed in colon cancer cell line, and SRSF7 knockdown inhibited growth and blocked cell cycle progression from G1 to S phase." (PMID 35463320, 2022). "Furthermore, SRSF7 regulated p21‐dependent cell cycle arrest in colon cancer cells." (PMID 35612714, 2022).
glioblastoma (2 papers, 2022 to 2025). The most malignant astrocytic tumor (WHO grade IV). "Furthermore, the two m6A sites of PDZ binding kinase (PBK) are regulated by SRSF7 in glioblastoma cells through recognition by IGF2BP2." (PMID 35625706, 2022). "SRSF7 gene expression is positively correlated with glioblastoma (GBM) cell-specific m6A methylation." (PMID 40129567, 2025). "Recently, it has been reported that serine/arginine-rich splicing factor 7 (SRSF7), an oncogenic splicing factor, promotes the proliferation and migration of glioblastoma cells dependent on the presence of the m6A methyltransferase." (PMID 35625706, 2022).
hepatocellular carcinoma (2 papers, 2024 to 2025). A malignant tumor that arises from hepatocytes. "Secondly, although the gene SRSF7 was identified as a key risk gene, its precise biological function and regulatory mechanism in hepatocellular carcinoma (HCC) remain unclear and warrant further in-depth investigation through functional experiments." (PMID 40649911, 2025). "Immunohistochemical staining further confirmed that SRSF7 was more highly expressed in hepatocellular carcinoma tissues." (PMID 38785569, 2024). "In addition, we knocked down the expression of SRSF7 in HepG2 and found that the viability of hepatocellular carcinoma cells was significantly reduced." (PMID 40649911, 2025). "Notably, SRSF7 has been found to be upregulated in hepatocellular carcinoma (HCC), yet its specific role and molecular mechanisms in HCC pathogenesis are not fully understood." (PMID 38785569, 2024).
liver cancer (2 papers, 2024 to 2025). An epithelial or non-epithelial malignant neoplasm that arises from the liver. "We found that the SRSF7 protein was highly expressed in liver cancer tissues using protein databases (CPTAC) and immunohistochemistry from clinical samples and that liver cancer patients with high SRSF7 protein expression had worse progression-free survival." (PMID 40649911, 2025). "These drugs may slow down or prevent the growth and metabolism of liver cancer cells by inhibiting the function of SRSF7 or PKM2." (PMID 38785569, 2024).
Alzheimer disease (1 paper, 2025). A progressive, neurodegenerative disease characterized by loss of function and death of nerve cells in several areas of the brain leading to loss of cognitive function such as memory and language. "In contrast, Srsf7 and Rpl19 have been found to be downregulated in microglia in Alzheimer's disease and are associated with homeostatic microglia." (PMID 40045485, 2025).
breast tumors (1 paper, 2016). "Analysis by immunohistochemistry of the expression of hnRNP A1, hnRNPH, RBM9/FOX2, SRSF1/ASF/SF2, SRSF2/SC35, SRSF3/SRp20, SRSF7/9G8 in breast tumors shows that the expression of hnRNP A1, but not the other tested RBPs, is associated with metastatic relapse." (PMID 26930004, 2016).
chronic lymphocytic leukemia (1 paper, 2015). "For example, exome-sequencing studies found that SF3B1 was mutated in 10–15% of patients with chronic lymphocytic leukemia, while other spliceosome genes (e.g. SRSF1, SRSF7 and U2AF65) were mutated at lower (but still detectable) frequencies in chronic lymphocytic leukemia patients." (PMID 26498691, 2015).
Diabetes (1 paper, 2025). "Diabetes downregulated the splicing factor serine/arginine-rich splicing factor 7 (Srsf7) in the PT." (PMID 40135071, 2025).
embryonic carcinoma (1 paper, 2025). "In transcriptome-wide RNA-binding profiles of selected SRSF proteins conducted in a murine embryonic carcinoma cell line, we noticed that SRSF7 interacts with Stmn2 based on iCLIP (individual-nucleotide resolution UV crosslinking and immunoprecipitation) results." (PMID 40140908, 2025).
gastric adenocarcinoma (1 paper, 2016). "Instead, SRSF7 in gastric adenocarcinoma was higher in intestinal-type, which has a higher survival rate than diffuse-type, and HNRNPA1 levels in CRC were higher in well-differentiated, without nodal involvement, or low-stage groups." (PMID 27282379, 2016). "In the semiquantitative immunoblot analysis, HNRNPA1 and SRSF7 levels were significantly higher in GC than in gastric normal mucosa, and SRSF7 levels were higher in intestinal-type compared with diffuse-type of gastric adenocarcinoma." (PMID 27282379, 2016).
head and neck cancer (1 paper, 2023). A primary or metastatic malignant neoplasm affecting the head and neck. "In head and neck cancer, reduction of core splicing factor expression caused by hypoxia (i.e., SF1, SRSF1, SRSF3, and SRSF7) results in nearly 90% of IR-affected genes displaying high retention of introns in hypoxic compared with normal cells." (PMID 37506056, 2023).
lymph node metastasis (1 paper, 2016). "We found a positive correlation between lymph node metastasis and expression of hnRNP A1 (p < 0.01) or SRSF7 (p < 0.01) and a negative correlation between lymph node metastasis and the expression of hnRNP H (p = 0.03) or SRSF3 (p < 0.01)." (PMID 26930004, 2016).
male infertility (1 paper, 2020). The inability of the male to effect fertilization of an ovum after a specified period of unprotected intercourse. "EGFR, the signalling dysfunction of which was associated with human male infertility, might be coregulated by FXR1, FXR2, and HNRNPA1 (all of these three bind EGFR from CLIP experiments), G3BP2, G3BP1, FMR1, and SRSF7." (PMID 32316190, 2020). "CFTR, mutations of which are associated with male infertility, might be coregulated by FXR1, HNRNPA1, MATR3, PABPC1, G3BP2, FMR1, and SRSF7." (PMID 32316190, 2020).
osteosarcoma (1 paper, 2024). A usually aggressive malignant bone-forming mesenchymal neoplasm, predominantly affecting adolescents and young adults. "Additionally, SRSF7 is not only involved in the progression of osteosarcoma but is also closely associated with UVM, READ, MESO, LGG, LIHC, ACC, immune cell infiltration, and immune pathways across multiple cancers." (PMID 39286028, 2024). "We identified 6 splicing factor genes associated with the prognosis of osteosarcoma patients, namely SRSF1, SRSF4, SRSF5, SRSF7, SRSF8, and SRSF10." (PMID 39286028, 2024). "Experimental results suggest that SRSF7 is a key factor influencing osteosarcoma proliferation and apoptosis." (PMID 39286028, 2024). "Silencing SRSF7 gene expression significantly inhibited cell proliferation in osteosarcoma cell lines, as demonstrated by plate colony formation and CCK-8 assays." (PMID 39286028, 2024). "SRSF7 is a significant gene influencing the occurrence and development of osteosarcoma." (PMID 39286028, 2024). "Although our study validated the effectiveness of SRs in predicting the prognosis of osteosarcoma patients through in vitro cell experiments and highlighted the oncogenic role of SRSF7 in osteosarcoma cells, there are still some limitations that point to directions for future research." (PMID 39286028, 2024). "In our previous study, we found that SRSF7 plays a significant regulatory role in osteosarcoma." (PMID 39286028, 2024). "Therefore, SRSF7 is expected to be a promising new therapeutic target in osteosarcoma treatment." (PMID 39286028, 2024). "si-SRSF7 was transfected into MG63 and SJSA-1 cell lines to investigate the effect of SRSF7 on the growth of osteosarcoma cell lines." (PMID 39286028, 2024).
prostate carcinoma (1 paper, 2020). A carcinoma that arises from epithelial cells of the prostate gland. "RASSF2, which is a tumor-suppressor in the prostate cancer mouse model, might be coregulated by FXR1, FXR2, HNRNPA1, PTBP1, G3BP1, HNRNPF, and SRSF7." (PMID 32316190, 2020).
Sepsis (1 paper, 2025). Sepsis is defined as life-threatening organ dysfunction caused by a dysregulated host response to infection. "SRSF7, E2F2, RAB13, and S100A8 were identified as potential pathogenic biomarkers of sepsis." (PMID 40909263, 2025). "RT-qPCR revealed decreased SRSF7 expression and increased RAB13, E2F2, and S100A8 expression in sepsis." (PMID 40909263, 2025). "The PBMC were separated of twenty patients with sepsis and twenty healthy volunteers, we estimated the mRNA expression level of SRSF7, E2F2, RAB13 and S100A8 in PBMC via RT-qPCR, the mRNA expression level of SRSF7(p<0.0001) was lower in the patients with sepsis than healthy people." (PMID 40909263, 2025).
cancer (14 papers, 2016 to 2025). A tumor composed of atypical neoplastic, often pleomorphic cells that invade other tissues. "Furthermore, to explore the association between SRSF7 and the clinical prognosis of 33 types of cancer patients, we performed univariate analysis using the TCGA dataset." (PMID 39286028, 2024). "Exposure to DNA damage inhibited Ex32 splice-in, potentiated the association of SRSF3 and SRSF7 with RIF1 pre-mRNA, and caused an increase in RIF1-S protein expression, which was also observed across a diverse set of primary cancers." (PMID 41489901, 2025). "The forest plot revealed that SRSF7 significantly influenced the overall survival (OS) of several specific tumor types among 28 cancer types, including UVM, READ, MESO, LGG, LIHC, and ACC." (PMID 39286028, 2024). "To further analyze the role of SRSF7 in other malignant tumors, we conducted a pan-cancer analysis of SRSF7." (PMID 39286028, 2024). "In this study, we first calculated the expression level of SRSF7 in cancer cells using the TCGA pan-cancer database." (PMID 39286028, 2024). "The results showed that SRSF7 was universally overexpressed in various tissues and cancer cell lines, especially in bone marrow tissue." (PMID 39286028, 2024). "Considering the limited number of normal samples in the TCGA database, we combined the GTEx and TCGA databases to conduct an in-depth study of SRSF7 expression in 27 types of tumors, revealing differential expression of SRSF7 in numerous cancers." (PMID 39286028, 2024). "When SRSF7 is present at high levels, such as in pluripotent cells or certain cancer cells, it binds upstream of pPASs and recruits FIP1, thereby acting as a sequence-specific enhancer of pPAS usage and promoting transcripts with short 3′UTRs." (PMID 33706811, 2021). "In the past studies, SRSF7 has been revealed to be heightened in carcinomas and promotes cancer progression in various tumors." (PMID 33842552, 2021). "It has been reported recently that SRSF7 plays a major role in proliferation of cancer cells and apoptosis." (PMID 30916337, 2019). "Currently, no reports have shown, with statistical significance, elevated levels of SRSF7 in any type of primary cancer or elevated levels of HNRNPA1 in primary GC samples." (PMID 27282379, 2016). "Furthermore, research has revealed that SRSF7 functions as an oncogene and is overexpressed in various cancers." (PMID 38740834, 2024). "Additionally, we described the regulatory role of SRSF7 in human pan-cancer." (PMID 39286028, 2024). "Additionally, we described the regulatory role of SRSF7 in pan-cancer." (PMID 39286028, 2024). "RIF1 alternative splicing was regulated by a suite of RNA-binding proteins, including serine and arginine rich splicing factor 1 (SRSF1), SRSF3, and SRSF7 whose expression and occupancy on RIF1 pre-mRNA changed in response to DNA damage and in primary cancers." (PMID 41489901, 2025). "In particular, in NSCLC, MALAT1 is involved in STAT3, SRSF7, and PBOV1 (prostate and breast cancer overexpressed 1) pathways; MALAT1 affects the levels of miR-124, miR-374b-5p, and miR-28-5p, which in turn, target STAT3, SRSF7, and PBOV1 mRNAs, respectively." (PMID 35630580, 2022). "Subsequently, we evaluated the differential expression of SRSF7 between cancer and non-cancer tissue samples in the TCGA database." (PMID 39286028, 2024). "In paired sample (cancer/NM from each same patient) comparison of stomach samples, only HNRNPA1 showed >50 % upregulation (cancer/NM >2) incidence (UI), followed by the other UIs in the order of HNRNPA1 (52 %), SRSF7 (42 %), and other SF proteins (22 %–33 %)." (PMID 27282379, 2016).
tumor (13 papers, 2016 to 2025). "A similar phenomenon is observed in SRSF7, a master splicing regulator implicated in tumor progression." (PMID 36284317, 2022). "This review enhances our understanding of the molecular landscape of SRSF7 in tumorigenesis with great potential to become a key node in tumor-targeted therapy and companion diagnostics, driving translational potential from mechanisms to clinical applications." (PMID 41469394, 2025). "Tumor cells with high and low expression of SRSF7 showed significant differences in apoptosis signaling pathways, in glycine, serine, threonine metabolism, and in glycerophospholipid metabolism pathways." (PMID 40649911, 2025). "SRSF7 is a core factor in the regulation of RNA splicing that affects the plasticity and metastatic potential of tumor cells through selective splicing." (PMID 40649911, 2025). "C1 SRSF7+ MC highly express DDX5, which had been shown to be associated with a variety of key tumor promoting molecular interactions and was involved in tumorigenesis and tumor progression signaling pathways." (PMID 39430754, 2024). "C1 SRSF7+ MCs were significantly more abundant in tumor tissues than in pericancer tissues in P1 and P3 samples, and this was confirmed by Ro/e preference analysis." (PMID 39430754, 2024). "Further grouping of the 5,001 MCs identified 8 distinct subtypes, including SRSF7-highly expressed MCs, which showed strong tumor preference and potential tumor-promoting properties." (PMID 39430754, 2024). "It turned out that the elevated E2F1 level under hypoxia is actually essential for the expression of splicing factor SRSF7, which in turn contributes to the spliceomic adaptation in response to tumor hypoxia." (PMID 34362878, 2021). "Additionally, this review examines the role of SRSF7 in the tumor immune microenvironment through alternative splicing and immune evasion through the immune checkpoint PD-1." (PMID 41469394, 2025). "Additionally, Western Blot analysis revealed changes in the expression of the proliferation marker PCNA, further supporting the regulatory role of SRSF7 in tumor cell proliferation." (PMID 39286028, 2024). "SRSF7 is abnormally expressed in various tumor tissues and plays a role in tumorigenesis." (PMID 38785569, 2024). "The violin plot showed the cell-cell interactions while giving the different ligands and receptors in the EGF signaling pathway, and the results showed that C1 SRSF7+ MCs subtype and tumor-cells were mainly contacted with AREG as a ligand and EGFR or ERBB2 as receptors." (PMID 39430754, 2024). "By targeting tumor cells and the C1 SRSF7+ MCs subtype for interactions analysis, we have identified the secretion of AREG ligands by a subtype of C1 SRSF7+ MCs in the EGF signaling pathway that act on the protein receptor EGFR on the membrane of the tumor cells." (PMID 39430754, 2024). "The results showed that there was a strong crosstalk between C1 SRSF7+ MCs and tumor cells." (PMID 39430754, 2024). "Our in vivo data also confirms increased expression of SRSF7 in hypoxic tumor regions." (PMID 34362878, 2021). "This suggested that C1 SRSF7+ MCs in EC might be involved in tumor promoting effect." (PMID 39430754, 2024). "The bar graphs illustrated that the C1 SRSF7+ MCs had the highest proportion of tumor tissues of P1 and P3 origin and was enhanced over the pericarcinoma tissues share, and similarly, the Ro/e preference graph corroborated this, suggesting that the C1 SRSF7+ MCs was more preferred to tumor tissues." (PMID 39430754, 2024). "Combined with the results of previous results in this paper, it can be concluded that the C1 SRSF7+ MCs and tumor cells crosstalk through the AREG-EGFR/AREG-(EGFR+ERBB2) signal pathway, thereby exerting a tumor-promoting effect." (PMID 39430754, 2024). "As can be seen from the Figure, C1 SRSF7+ MCs subtype had higher expression as a ‘sender’ in the EGF signaling pathway, whereas tumor-cells were acting as ‘receiver’, ‘mediator’ and ‘influencer’ in this signaling pathway." (PMID 39430754, 2024).
tumor (continued). "UCSC Xena analysis of the TCGA PRAD dataset (n = 623) showed significant upregulation of FBXO45, SRSF7 and MYBL2 mRNAs in the PCa tumor tissues 50–60% compared to normal." (PMID 35612714, 2022). "Median levels of other SF proteins, except HNRNPA1 and SRSF7, were not significantly different based on tumor status, lymph node metastasis, TNM stage, or aneuploidy status in both gastric and CR adenocarcinoma." (PMID 27282379, 2016).
SRSF7 also shares sentences with these, for which no sentence is quoted: acute myeloid leukemia (1 paper); adenocarcinoma (1); breast invasive carcinoma (1); colorectal cancer (1); corticobasal degeneration (1); esophageal cancer (1); infection (1); myeloma (1); neuroblastoma (1); neurodegenerative disease (1); non-small cell lung carcinoma (1); Pick disease (1); progressive supranuclear palsy (1).